Y_RNA (Y RNA )
Gene: Miscellaneous RNA gene on chromosome 5 (23,994,502 to 23,994,603, reverse strand). Ensembl gene ENSG00000200600.
Homologues: Orthologues: chimpanzee Y_RNA (98% identical), macaque Y_RNA (91% identical). Paralogues in human: RNY3 (85% identical), RNY3P1 (85% identical), Y_RNA (85% identical), Y_RNA (84% identical), Y_RNA (83% identical), Y_RNA (82% identical), Y_RNA (81% identical), Y_RNA (80% identical), RNY3P16 (79% identical), RNY3P4 (79% identical), Y_RNA (79% identical), RNY3P14 (78% identical), and 94 more.